FOXP1 (forkhead box P1)
Diseases named in the same sentence as FOXP1 in open-access papers (continued):
Sharing a sentence is not in itself a finding about the gene and the disease.
breast cancer (continued). "AKT/mTOR inhibition in breast cancer cell lines leads to decreased FOXP1 expression." (PMID 35122700, 2022). "Our observation may be in line with previous studies in breast cancer that observed high FOXP1 protein expression to be a favorable prognostic marker in patients with estrogen receptor (ER)-positive breast cancer." (PMID 31745703, 2020). "Along these lines, PRMT5 recruitment to the FOXP1 promoter facilitates FOXP1 expression via PRMT5-dependent H3R2me2s with concomitant WDR5/SET1/MLL complex-driven H3K4me3, implicated in maintenance of stemness in breast cancer stem cells (BCSCs)." (PMID 32743345, 2020). "In breast cancer, it is not clear how miRNAs regulate IRs and PD-1-associated transcriptional factor Foxp1 in CD8+ T cells." (PMID 31594465, 2019). "Similar results were obtained by immunofluorescence staining, with FOXP1 significantly accumulated in nucleus of adipocytes after cocultivated with breast cancer cells, while the PI3K/AKT inhibitor or tiplaxtinin decreased the distribution of FOXP1 in the nucleus." (PMID 31170987, 2019). "Therefore, we have focused on miRNAs targeting iR and Foxp1 gene expression in CD8+ T cells in murine 4T1 breast cancer cells in vitro; our data reveal that an miRNA has the capacity to enhance antitumour immunity by reversing CD8+ T-cell exhaustion." (PMID 31594465, 2019). "However, FOXP1 was found as a tumor suppressor in breast cancer and as an oncogene in MALT lymphoma." (PMID 31815635, 2019). "Our observations strongly indicated that FOXP1 expression might shift from the nucleus to the cytoplasm during breast tumorigenesis, and therefore, cytoplasmic mislocalization of FOXP1 is suggested play an important role in breast cancer progression." (PMID 29848352, 2018). "Studies on the mechanisms of FOXP1 subcellular relocalization in breast cancer are very few." (PMID 29848352, 2018). "Although N-FOXP1 expression in breast cancer has been documented in several studies, the expression patterns of FOXP1 protein at different stages of breast cancer progression, including DCIS and IDC, and in ADH and UDH lesions, have not yet been clearly demonstrated." (PMID 29848352, 2018). "In summary, cytoplasmic relocalization of the FOXP1 protein is a frequent event in breast cancer." (PMID 29848352, 2018). "However, in patients with breast cancer, the pooled result of three datasets showed that decreased FOXP1 expression was significantly correlated with an unfavorable RFS (HR = 1.93, 95%CI: 1.33–2.80, p = 0.001)." (PMID 27457567, 2016). "In addition, decreased FOXP1 expression was significantly correlated with an unfavorable relapse-free survival (RFS) in breast cancer patients (HR = 1.93, 95%CI: 1.33–2.80, p = 0.001)." (PMID 27457567, 2016). "Additionally, in patients with solid tumors such as breast cancer, decreased FOXP1 expression was also significantly correlated with an unfavorable RFS." (PMID 27457567, 2016). "FOXP1 also functions in the proliferation of MCF7 breast cancer cells." (PMID 25663935, 2015). "Furthermore, a number of correlation studies have demonstrated that the loss of FOXP1 protein expression is associated with a poor prognosis, however, the increased immunoreactivity of FOXP1 may predict a good response to tamoxifen treatment in breast cancer patients." (PMID 25663935, 2015). "Following treatment with wortmannin, an inhibitor of phosphatidylinositol 3-kinase (PI3K)/Akt, MCF7 and MDA-MB-231 breast cancer cells demonstrated decreased FOXP1 protein expression levels; this result was also observed in the small interfering (si)RNA silencing of Akt." (PMID 25663935, 2015). "In addition, FOXP1 co-expression with estrogen receptor significantly improved relapse-free survival,it suggests FOXP1 may function as a tumour suppressor in breast cancer." (PMID 35614183, 2022). "Similarly,a report confirmed that the increased FOXP1 protein expression could predict a good effect to tamoxifen in breast carcinoma patients." (PMID 35614183, 2022).
breast cancer (continued). "Furthermore, FOXP1 suppresses the antitumor function of interleukin 21 (IL-21) to stimulate the secretion of IFNγ from CD4+ T or CD8+ T cells in estrogen positive MCF-7 breast cancers." (PMID 31815635, 2019). "Interestingly, a recent study indicated that the majority of invasive breast cancers (67%, n = 133) showed a nuclear immunoreactivity of the estrogen-inducible FOXP151, whereby knockdown of FOXP1 suppressed and ectopic expression promoted breast cancer cell proliferation." (PMID 30057418, 2018). "Moreover, FOXP1 immunoreactivity may predict a favorable prognosis for breast cancer patients treated with tamoxifen." (PMID 29848352, 2018). "Thus, in conclusion, the PI3K/Akt signaling pathway should be considered as a target in the treatment of breast cancer, although additional studies are first required to determine the mechanism via which FOXP1 is regulated by the PI3K/Akt/p70S6K signaling pathway." (PMID 25663935, 2015). "In breast cancer stem cells, it was shown that PRMT5 functions to methylate H3R2, allowing SET1 binding and H3K4 trimethylation at the FOXP1 promoter to activate FOXP1 transcription both in vitro and in vivo." (PMID 37795443, 2023). "It is also frequently downregulated in solid tumors, including breast cancer, non-small cell lung cancer, oral squamous cell carcinoma, ovarian cancer, renal cell carcinoma, hepatocellular carcinoma and prostate cancer, which suggests that FOXP1 may act as a tumor suppressor." (PMID 27167345, 2016). "Assessment of cyclin D1, FOXP1, NRP1 and CD99 expression was repeated on a validation cohort of 82 BRCA1 and 65 sporadic basal-like breast cancers." (PMID 26152113, 2015). "Elevated expression of FoxP1 has been demonstrated in NSCLC, hepatocellular carcinoma and breast cancer." (PMID 23874428, 2013). "For example, in breast cancer, PRMT5 upregulates FOXP1 expression via H3R2me2s." (PMID 41513606, 2026). "FOXP1, FOXA1, and FOXM1 may be used as potential biomarkers to predict the prognosis of patients with breast cancer." (PMID 38608123, 2024). "Another significant result of this study revealed that FOXP3 expression predicted the breast cancer cells’ response to anticancer drugs, whereas FOXP1, FOXP2 and FOXP4 did not predict." (PMID 35614183, 2022). "In similar, MTX, Etoposide, Fulvestrant, and Resveratrol could suppress the expression of FOXD1, FOXA1, FOXM1, and FOXP1, respectively, which exhibited oncogenic potential in LGG, PRCA/breast cancer, LUAD/LUSC, and PAAD." (PMID 36292640, 2022). "Notably, circular RNA SHKBP1 was upregulated in malignant glioma targeting FOXP1 or FOXP2, while circular RNA ZNF609 and MYO9B were upregulated in renal cancer and breast cancer, respectively, targeting FOXP4." (PMID 31815635, 2019). "It is interesting to speculate that functional interactions between FOXP1 and the nuclear hormone receptors AR and ER17 may play a role in the 3p13-14 deletion’s prognostic significance in prostate and breast cancers and potentially others." (PMID 29057879, 2017). "In this study, we confirm that PRMT5 regulates the proliferation of bulk breast cancer cells and, more importantly, define a critical role for PRMT5 in the maintenance and propagation of BCSCs in vitro and in vivo through the epigenetic regulation of FOXP1." (PMID 29262329, 2017). "For example, FOXP1 is a tumor suppressor in lung cancer, pancreatic cancer, cholangiocarcinoma, prostate cancer, breast cancer, and neuroblastoma, but an oncoprotein in DLBCL and ovarian cancer, and sometimes also exhibit oncoprotein functions in breast cancer and prostate cancer." (PMID 39623140, 2025). "It is also possible that Foxp1 depletion may improve lymphocyte migration into the tumor microenvironment, as is the case in breast cancer where FOXP1 has recently been identified as a negative regulator of tumor infiltrating lymphocyte migration." (PMID 32309216, 2020).
breast cancer (continued). "However, the FOXP1 expression patterns at different stages of breast cancer progression are largely unknown, and the significance of cytoplasmic FOXP1 (C-FOXP1) expression in breast cancer has not been well illustrated." (PMID 29848352, 2018). "However, whether calpain II plays a role in FOXP1 regulation in breast cancer has not yet been documented." (PMID 29848352, 2018).
Intellectual disability (46 papers, 2010 to 2026). "A heterozygous de novo FOXP1 variant was identifed with exome sequencing in a patient with autism, intellectual disability, and severe speech and language impairment." (PMID 40642607, 2025). "FOXP1, a haploinsufficient and potentially triplosensitive transcription factor implicated in intellectual disability, exhibited a strong and dose-dependent response, particularly to varying levels of GFI1B." (PMID 38464330, 2025). "FOXP1 syndrome caused by FOXP1 haploinsufficiency is characterized by intellectual disability, speech, and language impairment, autistic features, and neuropsychiatric abnormalities such as anxiety and hyperactivity." (PMID 40568906, 2025). "The transcription factor encoded by FOXP1 is involved in a neurodevelopmental disorder that involves intellectual disability with autistic features, together with language impairment." (PMID 38565598, 2024). "Foxp1-specific deletions and mutations have been reported in patients with intellectual disability (ID), autism spectrum disorder (ASD), speech and language deficits." (PMID 38280977, 2024). "Mutations or deletions in the FOXP1 gene are associated with the occurrence of a wide range of disorders such as intellectual disability, autism spectrum disorders, hypotonia, dysmorphia, and heart disease." (PMID 38539661, 2024). "The open state of chromatin of the FOXP1 gene, dysfunction of which has been reported to be associated with intellectual disability and speech defects, was enriched in Purkinje cells." (PMID 37993461, 2023). "FOXP1 syndrome (Case 2) is associated with intellectual disability, language impairment, autism spectrum disorder, myotonia, mild dysplasia, and congenital abnormalities of the brain, heart, and urinary system." (PMID 37987334, 2023). "In this study, a de novo splicing variant (c.1652 + 5 G>A) of the FOXP1 gene was identified in a patient with global developmental delay, mild intellectual disability, speech delay, and autistic features." (PMID 35991577, 2022). "There were at least ten studies that screened individuals with autism spectrum disorder (ASD) and intellectual disability (ID) for FOXP1 deletions and mutations." (PMID 33892622, 2021). "Individuals with FOXP1 syndrome (including individuals with mutations or deletion impacting the FOXP1 gene) typically present with intellectual disability, speech and language deficits, hypotonia, features of ASD, and mild dysmorphic features." (PMID 34588003, 2021). "FOXP1 syndrome is associated with intellectual disability, language deficits, autism spectrum disorder, hypotonia, and congenital anomalies, including mild dysmorphic features, and brain, cardiac, and urogenital abnormalities." (PMID 33892622, 2021). "Heterozygous FOXP1 mutations lead to intellectual disability, speech deficits and autism spectrum disorder (ASD), and delayed motor development." (PMID 30753188, 2019). "We detected a novel de novo missense mutation (NM_001244815: c.G1444A, p.E482K) of FOXP1 in a patient with intellectual disability and severe speech delay." (PMID 31199603, 2019). "De novo FOXP1 mutations have been associated with intellectual disability (ID), motor delay, autistic features and a wide spectrum of speech difficulties." (PMID 29330474, 2018). "FOXP1 has also been implicated in several related cognitive phenotypes including language impairment and intellectual disability." (PMID 28540026, 2017). "Point mutations, deletions and other disruptions of the FOXP1 gene have been found in patients with global developmental delay, intellectual disability and autism spectrum disorders." (PMID 26010426, 2015). "Mutations of FOXP1 have been found in patients with global developmental delay, intellectual disability, and autism spectrum disorders." (PMID 26010426, 2015).
Intellectual disability (continued). "Genetic evidence emerging in the last 2 years provides compelling evidence that FOXP1 variants are responsible for a more global cognitive phenotype, encompassing language impairment, intellectual disability, ASD and motor development delay." (PMID 22736078, 2012). "Furthermore, the FOXP1 (Forkhead Box P1) gene has been implicated in several conditions, including intellectual disability, autism spectrum disorder, and congenital anomalies such as dysmorphic features and cardiac abnormalities." (PMID 39570887, 2024). "In addition to the deletion, a de novo nonsense mutation, R525X, was found in the FOXP1 forkhead domain in another patient with non-syndromic intellectual disability (IQ of 48), severe language impairment and ASD." (PMID 22736078, 2012). "Haploinsufficiency of FOXP1, either from an intragenic deletion, N-terminal deletion, a premature translational stop, a reading frame shift or other protein altering mutations has been found in cohorts of patients with intellectual disability and autism spectrum disorders." (PMID 26010426, 2015). "The FOXP1 gene has been implicated in neurodevelopmental disorders, such as ASD, and the FOXP1 syndrome, in individuals with the presence of autistic spectrum disorder traits, intellectual disability, language impairment, and psychiatric characteristics." (PMID 35205412, 2022). "In humans, mutations in FOXP1 and FOXP2 have been implicated in cognitive deficits including intellectual disability and speech disorders." (PMID 30753188, 2019). "Disruption of FOXP1 leads to cognitive dysfunction including intellectual disability and autism spectrum disorder together with language impairment." (PMID 31214170, 2019). "The patient reported here shares speech difficulties, intellectual disability and autistic features with other FOXP1 syndrome patients, and thus the diagnosis for this patient should be changed." (PMID 29330474, 2018). "Loss of Foxp1, specifically in pyramidal cells of the neocortex and CA1/2, is sufficient to cause autism spectrum disorder and intellectual disability behavior by impairing hippocampal LTP maintenance." (PMID 29674952, 2018). "Previous studies in individuals carrying FOXP1 mutations and deletions have described the presence of autism spectrum disorder (ASD) traits, intellectual disability, language impairment, and psychiatric features." (PMID 29090079, 2017). "Heterozygous disruptions of FOXP1 have been found in several patients with neurodevelopmental disorders, including intellectual disability, autism spectrum disorder, and motor development delay." (PMID 28126037, 2017). "Variants in FOXP1 and FOXP2 can lead to mental retardation with language impairment (MIM#613670) and Speech-language disorder-1 (MIM#602081), respectively." (PMID 27435318, 2016). "Shortly afterwards, a large-scale screen for copy number variations (CNVs) in 1,523 patients with intellectual disability, uncovered three de novo heterozygous deletions solely affecting FOXP1." (PMID 22736078, 2012). "This individual had severe ASD and delayed language development together with intellectual disability (IQ of 34), reminiscent of previously reported FOXP1 phenotypes." (PMID 22736078, 2012). "In addition, FOXP1 syndrome, caused by haploinsufficiency of the forkhead box P1 (FOXP1) gene, is a neurodevelopmental disorder that manifests as motor dysfunction, intellectual disability, language impairment, and autism." (PMID 37021129, 2023). "In the brain, the transcription factor, FOXP1, heterodimerizes with its paralog, forkhead box P2 (FOXP2), to form a transcription factor; rare mutations in FOXP2 have been reported in multiple cases of intellectual disability and language impairment." (PMID 38028628, 2023). "In 2009, Pariani and colleagues reported a child with intellectual disability (ID) and a multigenic deletion including the FOXP1 gene, and hypothesized that FOXP1 contributed to ID." (PMID 33892622, 2021).
Intellectual disability (continued). "Individuals with FOXP1 syndrome present with a complex and variable neurobehavioral profile characterized by mild to moderate intellectual disability, speech delays, motor impairments and high rates of neurobehavioral symptoms, which include ASD features, ADHD, and anxiety disorders." (PMID 34588003, 2021). "Our findings reinforce the neurobehavioral phenotype of FOXP1 syndrome as a condition characterized by mild to moderate intellectual disability, motor delays, language impairment, and a range of behavioral features that are characteristic of ASD, ADHD, and anxiety disorders." (PMID 34588003, 2021). "All non-verbal IQs reported in patients with FOXP1 variants are below this threshold indicating that intellectual disability is a consistent feature of the phenotype associated with FOXP1 disruption." (PMID 22736078, 2012). "However, in the last few years, novel rare disruptions in FOXP1 have been reported in multiple cases of cognitive dysfunction, including intellectual disability and autism spectrum disorder, together with language impairment." (PMID 22736078, 2012). "We aimed to report on previously unappreciated clinical features associated with FOXP1-related intellectual disability (ID) syndrome, a rare neurodevelopmental disorder characterized by global developmental delay, intellectual disability, and language delay, with or without autistic features." (PMID 37521304, 2023). "Haploinsufficiency of Forkhead box protein P1 (FOXP1), a highly conserved transcription factor, leads to developmental delay, intellectual disability, autism spectrum disorder, speech delay, and dysmorphic features." (PMID 30385778, 2018). "The disrupted coding sequences, altered expression, and association with congenital disease make it likely that the disruptions of FOXP1 and possibly DPYD contributed to the developmental delay and intellectual disability of the patient." (PMID 28126037, 2017). "FOXP1 syndrome (FOXP1S) is associated with “intellectual disability with language impairment and with or without autistic features” (OMIM #613670) and is caused by FOXP1 gene deletions and mutations (nonsense, missense, and in-frame deletions)." (PMID 33892622, 2021). "For example, the disrupted FOXP1 and DPYD genes are known MCA/MR genes that may have contributed to the intellectual disability and developmental delay in our patient." (PMID 28126037, 2017).